SLC17A7 (solute carrier family 17 member 7)
Description:
Multifunctional transporter that transports L-glutamate as well as multiple ions such as chloride, proton, potassium, sodium and phosphate. At the synaptic vesicle membrane, mainly functions as an uniporter which transports preferentially L-glutamate but also phosphate from the cytoplasm into synaptic vesicles at presynaptic nerve terminals of excitatory neural cells (By similarity). The L-glutamate or phosphate uniporter activity is electrogenic and is driven by the proton electrochemical gradient, mainly by the electrical gradient established by the vacuolar H(+)-ATPase across the synaptic vesicle membrane (By similarity). In addition, functions as a chloride channel that allows a chloride permeation through the synaptic vesicle membrane that affects the proton electrochemical gradient and promotes synaptic vesicles acidification (By similarity). Moreover, may function as a K(+)/H(+) antiport allowing to maintain the electrical gradient and to decrease chemical gradient and therefore sustain vesicular glutamate uptake (By similarity). The vesicular K(+)/H(+) antiport activity is electroneutral (By similarity). At the plasma membrane, following exocytosis, functions as a symporter of Na(+) and phosphate from the extracellular space to the cytoplasm allowing synaptic phosphate homeostasis regulation. The symporter activity is driven by an inside negative membrane potential and is electrogenic (By similarity). Is necessary for synaptic signaling of visual-evoked responses from photoreceptors (By similarity).
Synonyms: VGluT1; BNPI
Tractability: Antibody: UniProt places it where antibodies can reach, with high confidence; its Gene Ontology location is reachable by antibodies, with high confidence; UniProt predicts a signal peptide or a membrane-spanning region. PROTAC: ubiquitination databases record sites on it; its protein half-life has been measured.
Gene: Protein-coding gene on chromosome 19 (49,429,399 to 49,443,197, reverse strand). Ensembl gene ENSG00000104888.
Subcellular location: Cytoplasmic vesicle, secretory vesicle, synaptic vesicle membrane; Cell membrane; Synapse, synaptosome
Pathways (Reactome):
Neuronal System: Glutamate Neurotransmitter Release Cycle
Transport of small molecules: SLC-mediated transport of neurotransmitters
Gene Ontology:
Molecular function: sodium:phosphate symporter activity; chloride channel activity; L-glutamate transmembrane transporter activity; L-glutamate uniporter activity; neurotransmitter transmembrane transporter activity; phosphate ion uniporter activity; potassium:proton antiporter activity; extracellularly glutamate-gated chloride channel activity; secondary active transmembrane transporter activity; transmembrane transporter activity
Biological process: chloride transport; L-glutamate transmembrane transport; neurotransmitter loading into synaptic vesicle; neurotransmitter transport; phosphate ion transport; potassium ion transport; regulation of synapse structure or activity; sodium-dependent phosphate transport; synaptic transmission, glutamatergic; chloride transmembrane transport; excitatory postsynaptic potential; neural retina development; phosphate ion homeostasis; phosphate ion transmembrane transport; potassium ion transmembrane transport; proton transmembrane transport; regulation of synaptic vesicle endocytosis; sodium ion transmembrane transport; transmembrane transport
Cellular component: membrane; clathrin-sculpted glutamate transport vesicle membrane; excitatory synapse; plasma membrane; synaptic vesicle membrane; cerebellar mossy fiber; postsynapse; presynaptic active zone; synapse; synaptic vesicle
Genetic constraint (gnomAD): Loss-of-function variants: 14 observed, 58.38 expected, observed/expected ratio (o/e) 0.24, 90% interval 0.16 to 0.38. The upper end of that interval is the gene's LOEUF score, 0.38, which puts it in group 1 of 6, group 1 being the genes least tolerant of losing a copy. Missense variants: 498 observed, 796.85 expected, observed/expected ratio (o/e) 0.62, 90% interval 0.58 to 0.67. Synonymous variants: 353 observed, 324.77 expected, observed/expected ratio (o/e) 1.09, 90% interval 1 to 1.19.
Homologues: Orthologues: chimpanzee SLC17A7 (100% identical), macaque SLC17A7 (100% identical), guinea pig SLC17A7 (99% identical), dog SLC17A7 (99% identical), mouse Slc17a7 (99% identical), rabbit SLC17A7 (98% identical), pig SLC17A7 (97% identical), rat Slc17a7 (85% identical), tropical clawed frog slc17a7 (83% identical), zebrafish slc17a7a (80% identical), zebrafish slc17a7b (78% identical), Drosophila melanogaster VGlut (48% identical), and 43 more. Paralogues in human: SLC17A6 (77% identical), SLC17A8 (73% identical), SLC17A5 (33% identical), SLC17A4 (28% identical), SLC17A2 (26% identical), SLC17A3 (25% identical), SLC17A1 (24% identical), SLC17A9 (20% identical), SLC37A1 (16% identical), SLC37A4 (16% identical), SLC37A2 (15% identical), SLC37A3 (14% identical).
Diseases named in the same sentence as SLC17A7 in open-access papers:
SLC17A7 is named in the same sentence as 91 diseases in open-access papers, as found by Europe PMC text mining. Sharing a sentence is not in itself a finding about the gene and the disease. The quoted sentences say what the papers report.
schizophrenia (23 papers, 2008 to 2025). A major psychotic disorder characterized by abnormalities in the perception or expression of reality. "This study indicates the likely contribution of the GRIN2A, GRIN2B, GRM8, SLC1A2, and SLC17A7 genes to the development of clinical heterogeneity in schizophrenia." (PMID 36980845, 2023). "In the present study, we were able to detect the contribution of the GRIN2A, GRIN2B, GRM8, SLC1A2, and SLC17A7 genes of the glutamatergic system to determining the clinical heterogeneity of schizophrenia, which is important for the prognosis and outcome of the disease." (PMID 36980845, 2023). "Moreover, PDP suggested that subjects with lower levels of EAAT2 in conjunction with lower levels of SLC17A7 or Synapsin-1 were more likely to achieve higher probability of schizophrenia." (PMID 35217646, 2022). "For both α-HPy and α-CJe, several established schizophrenia candidate proteins with cross-reactivity to either of these antibodies could be identified including Syt5, Slc17a7, Stmn4, and Ncan." (PMID 32860155, 2021). "We examined the association of 39 single nucleotide polymorphisms in eight genes (GRIN2A, GRIN2B, SLC1A2, SLC1A3, SLC17A7, GRM3, GRM7, and GRM8) involved in the glutamatergic system with the development of clinical heterogeneity of schizophrenia." (PMID 36980845, 2023). "The molecules that mostly contributed to discriminate schizophrenia from controls were EAAT2, CAMK2A, Synapsin-1, l-Asn, GRIA2, GRIA4, and SLC17A7 whereas the ones that barely contributed to the discrimination were: Gly, mGluR5, CaMKIIα, VGluT1, and d-Asp." (PMID 35217646, 2022).
depression (18 papers, 2012 to 2025). "Three genes from the list (Slc17a7, Slc6a4 and Tph2) are associated with the terms abnormal fear/anxiety-related behavior and abnormal depression-related behavior." (PMID 32917038, 2020). "The same expression profile, i.e., a predicted decrease of GRIN2D and ZSWIM9 levels but increased SLC17A7 levels, was also associated with increased risk for AD, lower educational attainment, lower cognitive ability, and higher risk of major depressive disorder across several independent studies." (PMID 37794492, 2023). "Nevertheless, the results of the current study suggest that in a mouse model of depression (BDNF+/−), CXCL1 deletion and Slc17a7 reduction are related to the loss of excitatory neurons in the prefrontal lobe, whereas Ptbp1 downregulation correlates with neuronal regeneration." (PMID 35711916, 2022).
Anxiety (15 papers, 2012 to 2025). Intense feelings of nervousness, tension, or panic often arise in response to interpersonal stresses. "Knockout of the gene SLC17A7 in mice suggests an increase of anxiety in mice 129 * C57BL/6N SLC17A7 mutant mouse." (PMID 40560842, 2025).
glioma (7 papers, 2009 to 2023). A benign or malignant brain and spinal cord tumor that arises from glial cells (astrocytes, oligodendrocytes, ependymal cells). "SLC17A7 and glutamatergic signaling has been shown to be associated with glioma-related seizures and appears to be overexpressed in brain tissue samples of glioma patients with seizures." (PMID 37298344, 2023). "Functional analysis showed that overexpression of SLC17A7 in GBM cells reduced proliferation, migration and invasion potential of GBM cells, suggesting SLC17A7 is a potential target for glioma therapy and warrants further investigation." (PMID 25749033, 2015). "In addition, the silencing of the oncogenic H3K9me3 methyltransferase SETDB1, which reduces cell viability and survival, appears to significantly increase SLC17A7 mRNA levels in pediatric high-grade gliomas, further confirming its tumor suppressive role." (PMID 37298344, 2023).
glioblastoma (5 papers, 2015 to 2025). The most malignant astrocytic tumor (WHO grade IV). "In glioblastoma, OPALIN, LTF, IL2RA, and SLC17A7 were implicated in Temozolomide resistance through pathways related to epithelial differentiation and angiogenesis." (PMID 41020875, 2025). "Further, the known glioblastoma tumor suppressor SLC17A7 located on 19q was underexpressed." (PMID 29890994, 2018). "Similarly, the underexpression of SLC17A7 in oligodendrogliomas may counteract its known function as tumor suppressor reported for glioblastomas." (PMID 29890994, 2018). "In glioblastoma treated with Temozolomide, the models prioritized OPALIN, LTF, IL2RA, and SLC17A7 as candidate resistance related genes." (PMID 41020875, 2025). "Interestingly, it was found that although SLC17A7 is downregulated in glioblastoma (GBM) compared with normal brain tissues, it suppresses GBM cell proliferation, invasion and metastasis." (PMID 38705513, 2024).
autism (4 papers, 2020 to 2026). Persistent deficits in social interaction and communication and interaction as well as a markedly restricted repertoire of activity and interest as well as repetitive patterns of behavior. "Interestingly, SSBP3 expression in human brain, colocalizes with SLC17A7, a gene from the solute carrier family that has been associated with autism, suggesting a potential link between Ssdp and autism-related pathways." (PMID 37486945, 2023).
brain injury (2 papers, 2017 to 2023). Acute and chronic (see also brain INJURIES, CHRONIC) injuries to the brain, including the cerebral hemispheres, CEREBELLUM, and brain STEM. "Genetic polymorphisms in the genes contributing to plasticity and repair (APOE), synaptic connectivity (GRIN2A), calcium influx (CACNA1E), uptake and deposit of glutamate (SLC17A7) are potential biomarkers of concussion incidence and recovery rate." (PMID 30202567, 2017).
cerebrovascular disease (2 papers, 2020 to 2023). "Abnormality of solute carrier family 17 member 7 (SLC17A7), also known as VGLUT1, seems to be associated with cognitive function in patients with cerebrovascular disease." (PMID 37041519, 2023).
glaucoma (2 papers, 2019 to 2021). Increased pressure in the eyeball due to obstruction of the outflow of aqueous humor. "A downregulation of Slc17a7 mRNA levels was noted in the higher concentrated ONA group in our study, assuming that it might also play a crucial role in glaucoma neurodegeneration." (PMID 31137749, 2019).
Obesity (2 papers, 2023 to 2024). Accumulation of substantial excess body fat. "We looked for common genes between the up-DPpGCs in TS and TA, and the significant differentially expressed genes (DEGs) induced by exercise in SkM of old mice, and found four genes, ATP1A3, SLC17A7, SYN2, and COL24A1 from the up-DPpGCs in TS, that are related to neurotransmission and obesity." (PMID 36769072, 2023).
substance abuse (2 papers, 2015 to 2022). The use of a drug for a reason other than which it was intended or in a manner or in quantities other than directed. "DA- and cAMP-regulated neuronal phosphoprotein PPP1R1B and vesicular glutamate transporter SLC17A7 may be molecular targets for the treatment of substance abuse." (PMID 36362437, 2022). "Gene expression networks consisted of recognized substrates for addiction, such as the dopamine- and cAMP-regulated neuronal phosphoprotein PPP1R1B/DARPP-32 and the vesicular glutamate transporter SLC17A7/VGLUT1 as well as potentially novel molecular targets for substance abuse." (PMID 26041984, 2015).
colorectal cancer (1 paper, 2021). A primary or metastatic malignant neoplasm that affects the colon or rectum. "CircFMN2/miR-1182 may also regulate the progression of colorectal cancer by targeting CD44, GNG7, RB1, COL1A2, PLCB1, SLC17A7, and TERT." (PMID 34249673, 2021).
diabetic retinopathy (1 paper, 2019). "The positive effects of resveratrol on SLC17a7 expression imply a potential application of diabetic retinopathy intervention." (PMID 31304063, 2019).
Down syndrome (1 paper, 2019). "These images show comparisons between Down syndrome and normal fetal retinas for photoreceptors (RCVRN, OTX2) and bipolar cells (VSX2) amacrine cells (ELAVL3/4) and synapses (VGLUT/SLC17A7)." (PMID 30842553, 2019). "If there was accelerated development in the Down syndrome retinas, we would expect to see a greater number of VSX2+ bipolar cells, more mature photoreceptors (RCVRN) and an increase in VGLUT/SLC17A7 labeling, but we do not see these changes." (PMID 30842553, 2019).
oligodendroglioma (1 paper, 2018). A well-differentiated (WHO grade II), diffusely infiltrating neuroglial tumor, typically located in the cerebral hemispheres. "Many of these candidates (e.g. ELTD1, SDHB, SEPW1, SLC17A7, SZRD1, THAP3, ZBTB17) are likely to push, whereas others (e.g. CAP1, HBXIP, KLK6, PARK7, PTAFR) might counteract oligodendroglioma development." (PMID 29890994, 2018). "Interestingly, several of these genes (e.g. ELTD1, SDHB, SEPW1, SLC17A7, SZRD1, THAP3, ZBTB17) are likely to push, whereas other genes (e.g. CAP1, HBXIP, KLK6, PARK7, PTAFR) might restrict oligodendroglioma development." (PMID 29890994, 2018).
panic disorder (1 paper, 2020). An anxiety disorder characterized by multiple unexpected panic attacks with persistent concern of recurring attacks. "Therefore, it seems that SLC17A7 within this deletion may be a candidate causative gene in patients with panic disorders." (PMID 32223758, 2020).
tumor (12 papers, 2015 to 2025). "SLC17A7 is considered a tumor suppressor, and its overexpression has been shown to inhibit GBM cell proliferation and invasion." (PMID 41020875, 2025). "Downregulation of both mRNA and protein levels of SLC17A7 was observed in tumor cells compared to normal brain tissues, and it was suggested that cancer cells take advantage of bivalency to silence this gene, preventing its tumor-suppressive activity." (PMID 33430434, 2021). "We found that another solute carrier gene, SLC17A7, is also a candidate bivalent tumor suppressor gene." (PMID 25749033, 2015). "Finally, we identified SLC17A7 as a bivalent tumor suppressor gene in GBM by demonstrating its down-regulation at both the protein and RNA levels in GBM tissues compared with normal brain tissues." (PMID 25749033, 2015). "Finally, we identified SLC17A7 as a bivalent tumor suppressor gene in GBM, as it is down-regulated at both the protein and RNA levels in GBM tissues compared with normal brain tissues, and it inhibits GBM cell proliferation, migration and invasion." (PMID 25749033, 2015). "Finally, we showed that SLC17A7 and SLC8A2 are two bivalent tumor suppressor genes whose expression were down-regulated in GBM tissues compared with normal brain tissues." (PMID 25749033, 2015). "We found that SLC17A7 is down-regulated at both the protein and RNA levels in GBM compared with normal brain tissues, suggesting that it might be a tumor suppressor gene whose expression is down regulated in GBM to reduce its tumor suppressor activities." (PMID 25749033, 2015).
infection (9 papers, 2010 to 2024). The state of being infected such as from the introduction of a foreign agent such as serum, vaccine, antigenic substance or organism. "To determine whether infection with IAV affects synaptic protein composition, we analyzed the gene expression of the presynaptic glutamate transporter Slc17a7 (VGLUT1) over the course of infection." (PMID 34700379, 2021).
brain disorder (2 papers, 2014 to 2022). A disease affecting the brain or part of the brain. "Subgenual anterior cingulate cortex (sgACC) of human subjects without brain disorders were labeled using fluorescent in situ hybridization (FISH) for CRH and markers of excitatory (SLC17A7), inhibitory (GAD1) neurons, as well as markers of other interneuron subpopulations (PVALB, SST, VIP)." (PMID 35280164, 2022).
SLC17A7 also shares sentences with these, for which no sentence is quoted: epilepsy (8 papers); Stroke (8); Alzheimer disease (7); Cognitive impairment (7); Parkinson disease (6); diabetes (5); ischemia (5); memory impairment (5); cognitive decline (4); tauopathy (4); amyloid (3); hearing loss (3); hypothyroidism (3); psychiatric diseases (3); Tinnitus (3); age-related macular degeneration (2); brain ischemia (2); cancer (2); Cerebral ischemia (2); channelopathy (2); colon cancer (2); deafness (2); dementia (2); Huntington disease (2); neuroblastoma (2); neurological diseases (2); alcohol abuse (1); Atrophy (1); autonomic dysfunction (1); bipolar disorder (1).
A further 42 diseases each share a sentence with SLC17A7 in 1 paper.